MPG (N-methylpurine DNA glycosylase)
Description:
Hydrolysis of the deoxyribose N-glycosidic bond to excise 3-methyladenine, and 7-methylguanine from the damaged DNA polymer formed by alkylation lesions.
Synonyms: AAG; ANPG; MDG; ADPG; APNG; CRA36.1; PIG11; PIG16
Tractability: Small molecule: a high-quality ligand is known. PROTAC: ubiquitination databases record sites on it; its protein half-life has been measured; a small molecule that binds it is known.
Target class: Enzyme; Hydrolase
Gene: Protein-coding gene on chromosome 16 (77,007 to 85,851, forward strand). Ensembl gene ENSG00000103152.
Subcellular location: Cytoplasm; Mitochondrion matrix, mitochondrion nucleoid; Nucleus
Subcellular location (Human Protein Atlas): Nucleoplasm; Cytosol
Pathways (Reactome):
DNA Repair: Cleavage of the damaged purine; Displacement of DNA glycosylase by APEX1; Recognition and association of DNA glycosylase with site containing an affected purine
Gene Ontology:
Molecular function: DNA binding; protein binding; alkylbase DNA N-glycosylase activity; damaged DNA binding; DNA N-glycosylase activity; catalytic activity
Biological process: base-excision repair; depurination; DNA alkylation repair
Cellular component: cytosol; mitochondrion; nucleoplasm; cytoplasm; mitochondrial nucleoid; nucleus
Genetic constraint (gnomAD): Loss-of-function variants: 33 observed, 30.05 expected, observed/expected ratio (o/e) 1.1, 90% interval 0.83 to 1.47. The upper end of that interval is the gene's LOEUF score, 1.47, which puts it in group 6 of 6, group 1 being the genes least tolerant of losing a copy. Missense variants: 455 observed, 409.31 expected, observed/expected ratio (o/e) 1.11, 90% interval 1.03 to 1.2. Synonymous variants: 202 observed, 168.42 expected, observed/expected ratio (o/e) 1.2, 90% interval 1.07 to 1.35.
Homologues: Orthologues: chimpanzee MPG (96% identical), macaque MPG (88% identical), dog MPG (76% identical), guinea pig MPG (73% identical), rabbit MPG (73% identical), mouse Mpg (72% identical), rat Mpg (71% identical), zebrafish mpg (48% identical), tropical clawed frog mpg (47% identical).